MIR1182 (microRNA 1182)
Synonyms: hsa-mir-1182; MIRN1182
Gene: MicroRNA gene on chromosome 1 (231,019,828 to 231,019,924, reverse strand). Ensembl gene ENSG00000283799.
Homologues: Orthologues: chimpanzee ptr-mir-1182 (100% identical).